DDN (dendrin)
Description:
Promotes apoptosis of kidney glomerular podocytes. Podocytes are highly specialized cells essential to the ultrafiltration of blood, resulting in the extraction of urine and the retention of protein (By similarity).
Synonyms: KIAA0749
Tractability: Antibody: UniProt places it where antibodies can reach, with medium confidence; its Gene Ontology location is reachable by antibodies, with medium confidence. PROTAC: ubiquitination databases record sites on it.
Gene: Protein-coding gene on chromosome 12 (48,995,149 to 48,999,375, reverse strand). Ensembl gene ENSG00000181418.
Subcellular location: Cell projection, dendritic spine membrane; Cytoplasm; Endoplasmic reticulum membrane; Perikaryon; Nucleus
Subcellular location (Human Protein Atlas): Nucleoplasm; Cytosol
Gene Ontology:
Molecular function: protein binding; DNA-binding transcription factor activity, RNA polymerase II-specific; RNA polymerase II cis-regulatory region sequence-specific DNA binding
Biological process: regulation of transcription by RNA polymerase II
Cellular component: cell projection; cytoplasm; cytosol; nucleoplasm; dendrite; dendritic spine membrane; endoplasmic reticulum membrane; nucleus; perikaryon; plasma membrane; postsynapse; presynapse
Genetic constraint (gnomAD): Loss-of-function variants: 6 observed, 10.15 expected, observed/expected ratio (o/e) 0.59, 90% interval 0.32 to 1.17. The upper end of that interval is the gene's LOEUF score, 1.17, which puts it in group 5 of 6, group 1 being the genes least tolerant of losing a copy. Missense variants: 933 observed, 930.6 expected, observed/expected ratio (o/e) 1, 90% interval 0.95 to 1.06. Synonymous variants: 425 observed, 399.89 expected, observed/expected ratio (o/e) 1.06, 90% interval 0.98 to 1.15.
Homologues: Orthologues: chimpanzee DDN (99% identical), macaque DDN (96% identical), pig DDN (82% identical), dog DDN (79% identical), mouse Ddn (77% identical), rat Ddn (77% identical), guinea pig DDN (77% identical), rabbit DDN (67% identical).
Diseases named in the same sentence as DDN in open-access papers:
DDN is named in the same sentence as 18 diseases in open-access papers, as found by Europe PMC text mining. Sharing a sentence is not in itself a finding about the gene and the disease. The quoted sentences say what the papers report.
glioblastoma (2 papers, 2022 to 2025). The most malignant astrocytic tumor (WHO grade IV). "The genes DDN and SH3GL2 were found to be upregulated in the proneural subtype, while CACNA1E in the mesenchymal subtype of glioblastoma exhibits good prognostic potential." (PMID 35571016, 2022).
glomerular diseases (2 papers, 2018 to 2022). "The expression of dendrin in podocyte nuclei has been reported by studies on different glomerulopathies: focal segmental glomerulosclerosis, lupus nephritis, membranous nephropathy, IgA nephropathy (IgAN)/IgA vasculitis, and minimal change disease." (PMID 35455664, 2022). "Due to this fact, nuclear relocation of dendrin in glomerular diseases (GD) is possible marker of disease." (PMID 30458823, 2018). "We have examined dendrin expression pattern in all glomeruli of each type of glomerular diseases and have found the significant difference." (PMID 30458823, 2018). "We have found that dendrin translocation occurs in different types of glomerular diseases, including MCD, and dendrin expression presents in different patterns." (PMID 30458823, 2018). "Due to this fact, nuclear relocation of dendrin in glomerular diseases might be a marker of disease." (PMID 35455664, 2022). "Therefore, we assume that dendrin relocation is the response to glomerular injury, unrelated to type of the glomerular disease." (PMID 30458823, 2018). "Dendrin expression pattern was different in analyzed types of glomerular diseases and higher proportion of dendrin negative glomeruli significantly correlated to lower creatinine clearance." (PMID 30458823, 2018). "In our immunohistochemical pilot study of human glomerular diseases, we have noticed not only dual, but also negative dendrin expression in several glomeruli." (PMID 30458823, 2018).
IgA glomerulonephritis (2 papers, 2013 to 2018). Inflammation of a specific segment of glomeruli within the kidney. "In addition, in human patients with IgA nephropathy, dendrin has been reported to trasnlocate to nucleus, suggesting that dendrin has a role in the pathogenesis of this common renal disorder." (PMID 24376653, 2013).
autism (1 paper, 2022). Persistent deficits in social interaction and communication and interaction as well as a markedly restricted repertoire of activity and interest as well as repetitive patterns of behavior. "DDN is a significant gene validated to have a role in causing autism with properties to heal impaired bone density." (PMID 35571016, 2022).
chronic kidney failure (1 paper, 2018). "During glomerular injury, dendrin nuclear translocation promotes podocyte apoptosis, which is the main pathological mechanism of chronic kidney failure." (PMID 30458823, 2018).
coronary artery disease (1 paper, 2019). "Besides Dendrin, only two proteins, junctional protein associated with coronary artery disease (JCAD) and USP6 N-terminal-like protein (USP6NL), contain two canonical ‘PPxY’ motifs separated by exactly two residues." (PMID 31486770, 2019).
crescentic glomerulonephritis (1 paper, 2025). A histopathologic term for a pattern of diseases characterized by extensive crescent formation in the glomeruli; patients present clinically with rapid deterioration of renal function, and possible progression to end-stage renal failure within weeks or months. "In a rat model of crescentic glomerulonephritis (CGN) the downregulation of Magi2 was associated with an accumulation of Dendrin in the nucleus of podocytes." (PMID 40563084, 2025).
diabetic kidney disease (1 paper, 2023). Progressive kidney disorder caused by vascular damage to the glomerular capillaries, in patients with diabetes mellitus. "This is emphasized in data derived for the transcriptome analysis of human diabetic kidney disease, showing 16 of the 23 DDN genes we have identified in human podocyte experiments." (PMID 36633903, 2023).
kidney failure (1 paper, 2018). An acute or chronic condition that is characterized by the inability of the kidneys to adequately filter the blood. "We propose that dendrin translocation and its correlation with kidney failure and pathological parameters should be interpreted in the context of dendrin expression pattern, not only as an absolute number of dendrin positive nuclei." (PMID 30458823, 2018).
tumor (3 papers, 2012 to 2024). "Intriguingly, nearly all signature-related genes were significantly downregulated in the tumor tissue in both the TCGA and local cohort, except DDN and C1GALT1." (PMID 37735483, 2023). "Upregulated genes include WDR46 and DDN, both of which are highly and specifically expressed in CNS NB-FOXR2 patient tumor tissues compared to the other subtypes." (PMID 39220247, 2024).
cancer (2 papers, 2016 to 2022). A tumor composed of atypical neoplastic, often pleomorphic cells that invade other tissues. "Furthermore, pan-cancer analysis of the hub genes revealed three genes, namely, CACNA1E, DDN, and SH3GL2, which were predominantly downregulated in GBM but not identified in more than five cancer types, could also make them putative prognostic biomarkers for GBM." (PMID 35571016, 2022).
DDN also shares sentences with these, for which no sentence is quoted: colorectal cancer (1 paper); focal segmental glomerulosclerosis (1); glomerulosclerosis (1); Henoch Schönlein purpura (1); minimal change disease (1); renal disorder (1); renal failure (1).